TOMM34 (translocase of outer mitochondrial membrane 34)
Diseases named in the same sentence as TOMM34 in open-access papers (continued):
Sharing a sentence is not in itself a finding about the gene and the disease.
cancer (continued). "However, Tomm34 is transcriptionally regulated by NRF-1 and NRF-2 and these latter are implicated in directing metabolic reprogramming during stress and are often hyperactive in cancers." (PMID 30917858, 2019). "Overall, this study demonstrates a molecular link of the TOMM34/ATP5B‐ATP synthesis axis during metformin adaptation and provides promising therapeutic targets for metformin sensitization in cancer treatment." (PMID 36321555, 2022). "Recently, researchers have found Tomm34 is transcriptionally regulated by NRF-1 and NRF-2 under cancer stress and hyperactive condition during metabolic reprogramming." (PMID 34257607, 2021). "In a comparison of the control with cancer group (grade 4), the 5-marker panel (CCT3, PCMT1, TKT, TOMM34, UBA1) showed better sensitivity (0.90 and 0.90), specificity (0.93 and 1.00), error rate (8 and 4%), and AUC value (0.94 and 0.96) than the best single marker (TOMM34)." (PMID 37875819, 2023). "Indeed, we have examined several peptides derived from a variety of cancer-testis antigens that have the oncogenic activity, including KIF20A, DEPDC1, MPHOSPH1, URLC10(LY6K),TTK, KOC1(IMP3), CDCA1, RNF43, and TOMM34." (PMID 24237633, 2013).
tumor (6 papers, 2016 to 2023). "Previous studies have demonstrated the significantly positive association between the upregulated TOMM34 expression and poor outcome of tumor patients." (PMID 36321555, 2022). "TOMM34, a translocase of the outer mitochondrial membrane, was upregulated to promote tumor metastasis in response to metformin‐induced metabolic stress." (PMID 36321555, 2022). "Tumor cells with a compensatory increase of TOMM34 protein levels following metformin treatment exhibited an increase of OXPHOS, resulting in enhanced metastatic potential." (PMID 36321555, 2022). "To this end, we generated an orthotopic mouse model of HCC to evaluate the role of TOMM34 in tumor metastasis (Fig EV2B)." (PMID 36321555, 2022). "The higher expression of Tomm34 was consistently correlated with larger tumor size (p = 0.01 in HPV-positive OSCC and p = 0.004 in HPV-negative OSCC) and higher TNM classification (p = 0.008 in HPV-positive OSCC and p < 0.001 in HPV-negative OSCC)." (PMID 34257607, 2021). "IHC assays suggested that the protein level of TOMM34 was higher in lung metastases than the primary tumor, indicating that TOMM34 upregulation may be essential for tumor metastasis." (PMID 36321555, 2022). "We next evaluated the effects of Gboxin on TOMM34/ATP5B‐mediated tumor metastasis." (PMID 36321555, 2022). "Tomm34, as their co-chaperone, may also promote tumor growth by affecting the folding of Hsp70 and Hsp90." (PMID 34257607, 2021). "Tomm34 is considered to be increased as a component of compensatory adaptations to maintain normal rates of protein import in response to mitochondrial abnormalities in tumor." (PMID 34257607, 2021). "Disrupting TOMM34/ATP5B axis by Gboxin impaired the compensatory adaptive process and tumor metastasis in both HCC cell lines and PDX models." (PMID 36321555, 2022). "The higher expression level of Tomm34 was closely related with higher TNM classification of OSCC (p < 0.001) and larger tumor size (p < 0.001) in different HPV status." (PMID 34257607, 2021). "Thus, we speculate that since TOMM34 is upregulated in tumor cells with increased demand in nucleotide synthesis due to accelerated proliferation, the observed perturbation of DNA replication may be related to alterations in purine metabolism due to TOMM34 knockout." (PMID 36829477, 2023). "Notably, disturbing the interaction between TOMM34 and ATP5B using Gboxin, a specific OXPHOS inhibitor, increased sensitivity to metformin and suppressed tumor progression both in vitro and in vivo." (PMID 36321555, 2022). "The expression of Tomm34 was closely related with the TNM clinical stage of OSCC (p < 0.001), tumor size (p < 0.001), lymph node metastasis (p = 0.001), drinking history (p = 0.019), but not with pathology differentiation, age, gender, smoking history and site (p > 0.05)." (PMID 34257607, 2021). "The high expression of Tomm34 was closely related with the TNM classification of OSCC (p < 0.01) and tumor size (p < 0.01) both in HPV-negative OSCC and HPV-positive OSCC, while related with lymph node metastasis (p = 0.001) in HPV-negative OSCC and drinking history (p = 0.044) in HPV-positive OSCC." (PMID 34257607, 2021). "We also found that high Tomm34 levels correlate with pT status but not with presence of secondary tumour or response to therapy." (PMID 30917858, 2019). "Moreover, we found that Gboxin, an F1FO ATP synthase inhibitor, could disturb the interaction between TOMM34 and ATP5B, leading to impairment of the compensatory adaptive process and tumor metastasis in both HCC cell lines and PDX models." (PMID 36321555, 2022).
neurodegenerative disease (1 paper, 2023). A disorder of the central nervous system characterized by gradual and progressive loss of neural tissue and neurologic function. "Perturbation of the parkin–ubuquitin proteosomal pathway might provide clues to the association of TOMM34 with neurodegenerative diseases." (PMID 36829477, 2023). "Moreover, TOMM34 has been linked to neurodegenerative diseases and immune response." (PMID 36829477, 2023).
TOMM34 also shares sentences with these, for which no sentence is quoted: hepatocellular carcinoma (2 papers); lung carcinoma (2); bladder cancer (1); cholangiocarcinoma (1); esophageal carcinoma (1); gastric cancer (1); gastrointestinal disease (1); glioblastoma multiforme (1); head and neck squamous cell carcinoma (1); invasive breast carcinoma (1); kidney chromophobe (1); lung adenocarcinoma (1); lung squamous cell carcinoma (1); prostate carcinoma (1); rectal cancer (1); rectum adenocarcinoma (1); stomach adenocarcinoma (1); thyroid carcinoma (1); uterine corpus endometrial carcinoma (1).